IL6 (interleukin 6)
Diseases named in the same sentence as IL6 in open-access papers (continued):
Sharing a sentence is not in itself a finding about the gene and the disease.
lymphoma (continued). "Lymphoma-derived small EVs carrying molecules such as TGF-β, IL-6 and prostaglandin E2 (PGE2) highly affect DC differentiation, maturation and function." (PMID 31137912, 2019). "Our result showed high levels of IL-10, IL-6, IL-1β, and TNF-α in lymphoma patients compared with control." (PMID 30814315, 2019). "Two serum biomarkers (CCL11/eotaxin, IL-6) discriminate between CRMO, alternative diagnoses (acute leukemia, lymphoma, JIA, osteoarticular infections, and reactive or para-infectious arthritis), and healthy controls." (PMID 29250517, 2017). "Serum biomarkers CCL11/eotaxin and IL-6 differentiate between patients with CRMO, healthy controls, and alternative diagnoses (leukemia and lymphoma, osteoarticular infections, para-infectious arthritis, and JIA)." (PMID 29250517, 2017). "Here we show that KSHV-miR-K-12-10b and miR-K-12-12* bind to TLR8 and this induces the increased secretion of the IL-6 and IL-10 by the cultured BCP1 clonal lymphoma cell line positive for KSHV." (PMID 25476907, 2014). "Expression of B cell-stimulatory cytokines IL-1β, IL-6, IL-10, IL-12p40, IL-13 and TNFα and HIV proteins p17, gp120 and nef were elevated in the Tg mice with lymphoma." (PMID 23985023, 2013). "Increased circulatory IL-6 has been long established as a negative prognostic indicator in human lymphoma patients and simultaneous elevations of IL-6 and VEGFA are independent predictors of survival in aggressive NHL50,51." (PMID 40760075, 2025). "Regarding possible triggers, lymphoma-complicated CLS patients have elevated levels of various cytokines, such as granulocyte colony-stimulating factor (G-CSF), interleukin-6 (IL-6), interleukin-10 (IL-10), interferon-gamma (IFN-γ) and tumor necrosis factor alpha (TNF-α)." (PMID 39072323, 2024). "We found that compared with healthy people and uninfected lymphoma patients, IL-6 and IL-10 were significantly increased in G- bacterial infections, while IL-6 was significantly increased and IL-10 was not significantly increased in G+ bacterial infections." (PMID 35432366, 2022). "IL-10 was detected at the nonlymphoma ATA B cell stage, and the lymphoma stage showed strongly increased IL-10 expression and CD1b/Mac1+IL-6+IL-10++ in ATA B lymphoma." (PMID 36050343, 2022). "In contrast, lymphadenopathy was not the prominent feature of IL6-/-;Eμ-myc lymphomas, as diseased mice displayed lymphoma mainly in the thymus and spleen [70% and 60% of the cases, respectively]." (PMID 33651821, 2021). "Alternatively, cytokines such as IL-1, IL-6, TNF-α, and TGF-β, secreted directly by lymphoma cells, may lead to tubular injury and interstitial fibrosis." (PMID 34218814, 2021). "Similarly, upregulation of interleukin-6 and JAK/STAT signaling was reported as a resistance mechanism against PI3K inhibitors in lymphoma." (PMID 34221985, 2021). "Significantly, several of the miRNAs known to target BIM and PTEN [e.g. mmu-miR-18a-3, mmu-miR-92a-2-5p and mmu-miR-92b-3p] are upregulated in IL6+/+;Eμ-myc B cells as compared to their IL6-/-;Eμ-myc counterparts, and presumed to contribute to the BIM and PTEN suppression in IL6+/+;Eμ-myc lymphomas." (PMID 33651821, 2021). "When SIADH occurs in the context of malignant hematologic diseases (e.g., lymphomas, leukemia, MM, Waldenström’s macroglobulinemia (WM)), it is mainly ascribed to ectopic ADH secretion or increased interleukin-6 (IL-6) production from malignant cells, as well as to CNS infiltration." (PMID 33228240, 2020). "It has been reported that capsaicin can induce the apoptosis of KSHV-positive primary lymphoma by inhibiting ERK and p38 MAPK signal transduction and IL-6 expression, inhibit ERK and p38 MAPK phosphorylation, and thus significantly inhibit the growth of primary lymphoma cells." (PMID 33061854, 2020).
lymphoma (continued). "It has been suggested that the suppressive functions of MDSCs could have been promoted by HSP72 expressed at the surface of lymphoma-derived small EVs which activate STAT3 pathway and stimulate the production of IL-6 in a TLR2/MyD88-dependent manner." (PMID 31137912, 2019). "Conversely, IL-6 levels did not demonstrate any statistical difference between those patients with uveitis and those with lymphoma, although they tended to be higher in eyes with uveitis." (PMID 23750271, 2013). "While negative IL-10 and IL-10/IL-6 values do not exclude a diagnosis of lymphoma, elevated levels do appear to be consistent with lymphoma clinically." (PMID 23750271, 2013). "The results demonstrated that both lymphoma-like and non-lymphoma dnTGFβRII IL-6−/− mice displayed restricted Vβ repertoires." (PMID 23145171, 2012). "NK1.1+ lymphoma-like T cells isolated from the liver had a markedly reduced ability to produce IFN-γ and IL-2 compared to NK1.1− lymphoma-like cells and HMNCs of non-lymphoma dnTGFβRII IL-6−/− mice, while such difference was not seen in the spleen." (PMID 23145171, 2012). "Furthermore, the pro-inflammatory cytokines interferon-γ (IFN-γ), tumor necrosis factor-α (TNF-α), and interleukin-6 (IL-6) in HL and NHL patients were studied and compared to those of healthy controls to further understand the role of cytokines in the pathogenesis of lymphoma." (PMID 35692834, 2022). "In sum, the Tandab(IL-6/CD20) protein could target CD20-positive DLBCL cells, as well as inhibit IL-6-related signaling pathway and eliminate the promoting effect of IL-6 on lymphoma cells." (PMID 36104733, 2022). "The data indicate that without IL-6, the Eμ-myc lymphomas are more dependent on the mTOR pathway." (PMID 33651821, 2021). "We reasoned that the pre-tumor setting rather than the MYC-driven lymphoma setting may more faithfully reflect the role of IL-6 in the earliest steps of Eμ-myc tumorigenesis." (PMID 33651821, 2021). "Importantly, mice lacking both CD37 and IL-6 were fully protected against lymphoma development, which confirms the involvement of the IL-6 pathway in driving tumorigenesis." (PMID 33333768, 2020). "Also, we found an evidence for the diagnostic utility of the following markers: MCP-1, eotaxin, IL-10 and IL-6 for NHL and HL and IL-1β for HL, while TNF-α has limited utility due to the poor ability to discriminate amongst patients with lymphoma and healthy control, as well as IL-1β for NHL." (PMID 30814315, 2019). "None of the MISTRG recipients lacking expression of IL‐6 showed evidence of lymphoma engraftment." (PMID 31515941, 2019). "Using murine splenic B cells and the mouse lymphoma CH12F3-2 CSR system, we identified that vIL-6, but not murine IL-6, increased class-switching, which correlated with upregulated AID expression." (PMID 30619193, 2018). "We further explored DLCBL proliferation by treatment with DCZ3301 in the presence or absence of interleukin-6 (IL-6) and insulin-like growth factor-1 (IGF-1), given that cytokines have an important role in lymphoma growth and survival." (PMID 29022919, 2017).
Parkinson disease (176 papers, 2005 to 2026). A progressive degenerative disorder of the central nervous system characterized by loss of dopamine producing neurons in the substantia nigra and the presence of Lewy bodies in the substantia nigra and locus coeruleus. "The pathophysiology of Parkinson’s disease is associated with increased neuroinflammation, such as IL6 signalling through the JAK/STAT pathway." (PMID 38977662, 2024). "Several studies have shown that neuropathological changes such as AD and Parkinson's are also associated with faulty inflammatory processes such as increased expression of the proinflammatory cytokine IL-6 in the brain." (PMID 33574982, 2021). "Increased IL-6 levels have been associated with disease severity in congestive heart failure and mortality in Parkinson’s disease." (PMID 32536956, 2020). "On the one hand, IL-6-deficient mice are more susceptible to the 1-methyl-4-phenyl-1,2,3,6-tetrahydropyridine-induced Parkinson’s disease model, suggesting neuroprotective actions of IL-6." (PMID 28438224, 2017). "IL-6-mediated inflammation is known to cause a higher incidence of gliosis and dendritic damage in patients with Parkinson's disease (PD), amyotrophic lateral sclerosis, multiple sclerosis and Alzheimer Disease." (PMID 21712995, 2011). "Indeed, diseases such as Alzheimer’s and Parkinson’s have been associated with heightened microglial activation, astrogliosis, and increased expression of TNFα, IL-1β, and IL-6." (PMID 39376599, 2024). "Importantly, the activation of the cGAS/STING pathway by circular cell-free mtDNA release, measured as an increase in proinflammatory Interleukin 6 (Il-6) levels has been confirmed in Parkinson’s disease patients with PARK2/PARK6 mutations." (PMID 34943897, 2021). "Indeed, increased activation of IL-6 trans-signaling in the brain has been implicated in several inflammatory age-related diseases of the nervous system, including Alzheimer’s and Parkinson’s Disease (c.f.,)." (PMID 34551810, 2021). "Moreover, increased IL-6 expression in the brain is linked with the profound neuropathological changes found with Alzheimer's and Parkinson's disease." (PMID 32655767, 2020). "However, in vivo, IL-6 showed beneficial effects in early stages of disease due to induction of plaque clearance and IL-6-deficient mice showed enhanced neuronal vulnerability in a MPTP-induced Parkinson model." (PMID 31396076, 2019). "Levels of IL-6 in serum and cerebrospinal fluid have been found to be elevated in stroke patients and the cytokine has also been implicated in the etiopathology of neurodegenerative disorders such as Alzheimer's disease (AD), Parkinson's disease (PD) and HIV encephalopathy." (PMID 15833109, 2005). "In a Parkinson's disease mouse model, paquinimod treatment downregulated the expression of inflammatory cytokines (IL‐6, IL‐1β and TNF‐α) and suppressed the TLR4/NF‐κB signalling pathway." (PMID 41582634, 2026). "The obtained results reinforce the existing clinical evidence that Alzheimer's and Parkinson's diseases are accompanied by an inflammatory response, with considerably higher blood levels observed for pro-inflammatory cytokines: IL-6, TNF-α and IL-1β." (PMID 39751856, 2024). "The levels of tumor necrosis factor-α and IL-β (including IL6) are significantly increased in Parkinson’s disease, a neurodegenerative disease." (PMID 38892402, 2024). "An increase in the appearance of proinflammatory cytokines like TNF-α and IL-6 is closely correlated with the development of Parkinson’s disease, according to prior research." (PMID 38551975, 2024). "Antibody targeting of astrocyte IL-6 has potential to prevent midbrain neuronal death in Parkinson's disease." (PMID 38329129, 2024). "OSAS exacerbates Parkinson’s disease; sleep disturbance severity and motor dysfunction have been related to IL-6 levels." (PMID 36982552, 2023).
Parkinson disease (continued). "For instance, in the case of Parkinson’s disease, there is a correlation between the degeneration pathway of dopaminergic neurons due to neuroinflammation mechanisms, such as increased systemic IL6 level." (PMID 36697403, 2023). "Asarone, galangin, baicalein, and a-mangostin reduced oxidative stress and pro-inflammatory cytokines, such as interleukin (IL)-1, IL-6, and tumor necrosis factor-alpha in M1-activated microglia in Parkinson’s disease." (PMID 37744008, 2023). "Meanwhile, Mucispirillum sp. was enriched in the patients with Parkinson’s disease, and it was negatively correlated with cognitive ability and positively correlated with the level of IL-6 in the brain cortex." (PMID 36673515, 2023). "Previous MR studies on Alzheimer’s disease suggest potential causal associations with BIN1, CCL27, C3, CD33, CD4 T cells, GDF-15 and SVEP1, whereas MR studies on Parkinson’s disease suggest a potential causal association with GPNMB, IL-6 and MIP1b." (PMID 37118290, 2022). "The analysis of the PPI network and MCODE displayed that these proteins were tightly related to the cell cycle, oocyte meiosis, Parkinson’s disease, apoptosis, the longevity regulating pathway and interleukin-6 signalling." (PMID 35525953, 2022). "Studies in Parkinson's disease have reported similar attenuation of the circulating levels of cytokines IL‐1b, IL‐6 and TNF‐a in LPS treated mice." (PMID 36426551, 2022). "Biofluid studies also support the role of neuroinflammatory processes in Parkinson's disease, with elevated levels of IL-2, IL-6, and TNF-α in the serum of patients with PD." (PMID 34725564, 2021). "The data presented show that the explored variants of parkinsonism, such as PD, PSP and MSA, share similarities in the pathogenic neuroinflammation, such as an increase in the proinflammatory factors IL-1, IL-6 and TNF-α." (PMID 33809527, 2021). "Injection of miR-155-5p agomir increases TNF-α, IL-1β, and IL-6 amounts in the ventral midbrain of Parkinson’s disease mice." (PMID 33692340, 2021). "This is in agreement with a study where fisetin administration has decreased IL-6 levels in the brain tissue of an animal model of Parkinson's disease." (PMID 34354662, 2021). "Of note, IL-1/IL-6 are increased in neurodegenerative disorders such as Alzheimer’s and Parkinson’s disease, as well as in cognitive dysfunction." (PMID 33324408, 2020). "In the rotenone induced Parkinson's disease rat model, not only the levels of IL-6, IL-1β, and TNF-α in striatum were improved, but the level of GABA, DA, NE, and 5-HT was significantly increasing when treatment with spermidine compared with model group." (PMID 32625082, 2020). "This suggests that microglia secrete, in particular, IL-6 at an early Parkinson stage, but probably also IL-1β." (PMID 33716638, 2020). "Female patients with Parkinson’s disease (PD) showed elevated levels of IL-1α, IL-2 and IL-6 while male patients with PD showed elevated levels of only IL-4 compared to healthy controls." (PMID 28196514, 2017). "CCL2, by reducing glutamate levels increased by N-methyl-d-aspartate (NMDA) and Tat protein, and IL-6, by preventing ROS and Ca2+ excitotoxicity in Parkinson’s and Huntington’s diseases, exert neuroprotective properties." (PMID 29228979, 2017). "IL-6, although undetectable in the naïve CNS, may contribute to physiological processes such as astrogliogenesis and neuronal differentiation and has also been implicated in a variety of chronic CNS diseases including MS, Alzheimer’s, Parkinson’s, and Huntington’s diseases." (PMID 25896970, 2015). "IL-6 and TNF-α have also been shown to play a role in the neuroinflammation associated with Parkinson's disease." (PMID 25478286, 2014). "We recently reported that patients with Parkinsońs disease (PD) have significantly higher median serum levels of IL-6 than healthy controls." (PMID 23626805, 2013).
Parkinson disease (continued). "Similarly, citronellol demonstrated suppression of TNF-α, IL-1β, and IL-6 in a Parkinson’s disease model, indicating a direct action in disrupting the NF-κB-mediated inflammatory cascade." (PMID 40656940, 2025). "The role of chronic inflammation is substantiated by a growing body of evidence in Parkinson's disease, where raised inflammatory markers, such as interleukin-6 and tumor necrosis factor-alpha, have been observed in association with greater severity of fatigue." (PMID 40276401, 2025). "Moreover, in a clinical study, the measurement of growth factors and interleukins, especially IL-6, showed significant changes in Parkinson’s patients." (PMID 37936189, 2023). "The previous study showed that IL-6 may affect neuronal function in Parkinson’s disease patients who have higher IL-6 expression in ventricular cerebrospinal fluid." (PMID 35453404, 2022). "In contrast, a recent study has shown that TRPV1 modulates M1/M2 macrophage polarization and decreases the levels of M1 macrophage markers, inducible nitric oxide synthase (iNOS) and interleukin-6 (IL-6), to promote dopaminergic neurons survival in a Parkinson’s disease model." (PMID 34006826, 2021). "It has been shown that in patients with Parkinson's disease, IL-6 correlates positively with motor symptoms severity, while IL-17 correlates with non-motor symptoms, specifically mood and cognition scores, with a negative correlation reported between IL-17 and cognitive deterioration." (PMID 35237183, 2021). "IL-6 induces a down-regulation of ZnT10 and enhances the accumulation of Mn2+ that might be correlated with Parkinson’s disease." (PMID 32915786, 2020). "Moreover, βHB can also suppress mRNA expression of the inflammatory cytokines TNF-α, IL-1β, and IL-6 in the microglia of a rat model of lipopolysaccharide-induced Parkinson’s disease." (PMID 29443873, 2018). "In addition to infectious and autoimmune neurologic disorders, neurodegenerative diseases, such as Huntington’s disease and Parkinson’s disease, are reported to show increased CSF IL-6 levels." (PMID 28438224, 2017). "We used 1-methyl-4-phenyl-1,2,3,6-tetrahydropyridine (MPTP), a neurotoxin that induces Parkinson disease, to evaluate the change of midbrain structure and the behavior of the anti-inflammatory factor e-cadherin, interleukin-6, tyrosine hydroxylase, phosphatase and tensin homolog, and caveolin-1." (PMID 27194825, 2016). "Consistent with the previous data discussing the elevated levels of IL-6 in the CSF in patients with Parkinson’s disease, it can be concluded that our observations could be potentially related to the occurrence of a non-specific compensatory mechanism which promotes a neuroregenerative phenotype." (PMID 38642286, 2024). "Several studies have confirmed that abnormal IL-6, CRP, TNF-α, IL-4, IL-8, and TGF-β levels were associated with worse motor function assessed by the Unified Parkinson’s Disease Rating Scale (UPDRS), whereas CRP and fractalkine might be potential markers of freezing of gait (FOG)." (PMID 36739284, 2023). "Moreover, the neuroprotective effects of estrogens may be inhibited by interfering with the production of interleukin-6 and increasing inflammation, and play an important role in the development and progression of Parkinson disease." (PMID 36941653, 2023). "In a principal component analysis (PCA) study of patients with early Parkinson’s Disease (PD), compared with healthy control subjects, the PC with elevated IL-2 and IL-6 was associated with faster progression of Non-Motor Symptoms Scale total and mood/apathy domain scores." (PMID 36572691, 2022). "In murine models of neurodegenerative Parkinson’s disease, the intrathecal graft of hDPSCs ameliorated behavioral deficits and dopaminergic (DA) neuron loss, by upregulating anti-inflammatory cytokines IL2, IL4, and TNF-β and reducing IL-1α, IL- 1β, IL6, IL8, and TNF-α pro-inflammatory ones." (PMID 33805573, 2021).